SIK2 (salt inducible kinase 2)
Diseases named in the same sentence as SIK2 in open-access papers (continued):
Sharing a sentence is not in itself a finding about the gene and the disease.
tumor (continued). "The depletion of SIK2 significantly enhanced radiation‐induced apoptosis and tumor regression." (PMID 39877288, 2025). "Moreover, SIK2 can regulate signal transduction, cell cycle, tumor formation, melanin production, neuronal injury repair, autophagy, and apoptosis." (PMID 37706195, 2023). "Furthermore, SIK2 has important roles in cell cycle, tumor, melanogenesis, neuronal damage repair, and apoptosis." (PMID 37706195, 2023). "In addition, it has also been shown that induced activation of oncogenic Ras and Src in the Drosophila eye epithelia resulted in small benign tumors, however when co-expressed with Sik2-CA resulted in tumor overgrowth." (PMID 37854071, 2023). "Together, our results demonstrate the efficiency and potency of the newly designed SIK2 inhibitor MRIA9 and confirm the benefit of combining SIK2 inhibition with a taxane-based treatment as a new tumor-suppressing strategy in this highly lethal gynecological disease." (PMID 34359562, 2021). "Thus, our data identify SIK2 as a novel tumor suppressor in GC and provide important insights into the mechanisms of GC development and progression as well as highlighting the potential target for therapeutic interventions." (PMID 33128264, 2021). "Considering the important roles of fatty acid and cholesterol synthesis in tumor growth, we hypothesized that SIK2 might promote OC growth through enhancing fatty acid and cholesterol synthesis." (PMID 31932581, 2020). "SIK2 modulates several subtle cellular signaling pathways, and its abundant expression in melanoma and ovarian tumors is suggestive of its pivotal function in tumor development." (PMID 30723708, 2019). "As a consequence, SIK2 may act as both tumor promoter and suppressor due to the diversity of cancer cell types or different genetic background." (PMID 30723708, 2019). "Moreover, a few small-molecule SIK2 inhibitors have been found to be able to rescue the oncogenicity of SIK2 during tumor development and reverse its abnormal activation of downstream pathways." (PMID 30723708, 2019). "This work may provide new ideas for targeting SIK2 as a novel therapeutic strategy in tumor therapy." (PMID 30723708, 2019). "Strikingly, mitotic activity was high in tumor regions in which SIK2 is lost." (PMID 29774109, 2018). "Some reports suggest an oncogenic role of SIK2 in different tumor types." (PMID 29774109, 2018). "Thus, we conclude that aberrant loss of SIK2 may contribute to hyper-activation of Ras/ERK and PI3K/Akt signaling pathways, thereby, takes part in tumor development via perturbing the delicate balance between proliferation and survival of breast cells." (PMID 29774109, 2018). "Compared to the individual drug, Erianin combined with 5-FU notably inhibited the expression of LKB1, SIK2, SIK3, and PARD3 in mouse tumor tissues." (PMID 39063214, 2024). "IHC and western blot analyses revealed that Erianin inhibited the expression of LKB1, SIK2, SIK3, and PARD3 in a dose-dependent manner in the mouse tumor tissues, and 5-FU also significantly reduced the levels of these proteins." (PMID 39063214, 2024). "Protein and gene expression analyses in patient samples revealed that SIK1, SIK2, SIK3, and PARD3 were all highly expressed in tumor tissues compared to adjacent normal tissues (p < 0.01)." (PMID 39063214, 2024). "Salt‐inducible kinase 2 (SIK2) belongs to the serine/threonine protein kinases of the AMPK/SNF1 family, which has important roles in cell cycle, tumor, melanogenesis, neuronal damage repair and apoptosis." (PMID 37706195, 2023). "Next, the expression levels of SIK2, MYLK, MYLK‐pS343, MYL2 and MYL2‐pS19 in tumour lysates were assessed by western blot and immunohistochemistry." (PMID 35278271, 2022). "The results of the analysis showed that there was a significant decrease in the levels of MYLK‐pS343 and MYL2‐pS19 in tumour lysates from OVCAR8‐shSIK2 cells compared to OVCAR8‐shNC cells, suggesting that SIK2 regulates MYLK/MYL2 phosphorylation." (PMID 35278271, 2022).
tumor (continued). "FTO inhibited autophagy of ccRCC cells and promoted tumor progression through an m6A-IGF2BP2-dependent mechanism, and SIK2 was their m6A target." (PMID 36360294, 2022). "SIk2 inhibitor ARN-3261 enhances sensitivity to carboplatin of both carboplatin-sensitive and resistant ovarian cancer cells in vitro, inhibits tumor xenograft growth and enhances sensitivity to both carboplatin and paclitaxel in in vivo xenograft models." (PMID 33503955, 2021). "Remarkably, silencing SIK2 improved PTX sensitivity and inhibited tumor growth, and this action was abolished by miR-654-5p inhibition, suggesting that SIK2 is a downstream target of UCA1/miR-654-5p." (PMID 32854207, 2020). "In order to assess if the identified kinases in the invasion assay correlate with expression levels in tumors from GC patients, mRNA and protein expression levels for FRK, DDR1, SIK2 and SRC were assessed in tumor samples from GC patients." (PMID 32082487, 2020). "When tumor growth was assessed 5 weeks post injection, we observed that MDA-MB-231 cells with elevated SIK2 levels formed significantly smaller tumors in weight and volume as compared to control injections." (PMID 29774109, 2018). "However, CD10, KHDRBS3, PCLAF, PSMA, SIK2 and GDF15 were differentially expressed with PCa progression, emphasising their roles in promoting tumour growth, invasion and metastasis." (PMID 39578642, 2025). "To further assess the clinical significance of FTO-SIK2-autophagy axis promoting ccRCC progression, we examined the expression of FTO and SIK2 in tumor tissues of patients with ccRCC and subsequently categorized the samples into FTO-low and FTO-high groups and determined their relevance in ccRCC." (PMID 36263177, 2022). "Levels of FRK, DDR1 and SRC expression on both mRNA and protein level were significantly higher in metastatic patient samples regardless of the tumor stage, while expression levels of SIK2 correlated with tumor size." (PMID 32082487, 2020). "Moreover, spearman rank correlation analysis also showed a positive correlation of expression levels between SIK2 and SREBP2 in tumor tissues from 121 OC patients (r = 0.254, p = 0.005)." (PMID 31932581, 2020). "Contrary, transcript and protein levels of SIK2 correlated with tumor size, but not metastasis of GC." (PMID 32082487, 2020). "Conversely, signal for the proliferation marker Ki67 was strongly detectable in ER/PR (+) tumor areas where no SIK2 expression is detectable." (PMID 29774109, 2018). "Molecular factors such as PTPRH, CPNE1, APLN, PLOD1, SPAG4, B7‐H3, and SIK2 have been shown to facilitate carcinogenesis and glycolysis via PI3K/AKT induction, whereas inhibitors of this pathway reduce glycolytic flux, diminish tumor growth, and increase sensitivity to anticancer drugs." (PMID 40740483, 2025). "We found that no SIK2 signal was detectable in all tumor samples that are classified as TNBC." (PMID 29774109, 2018). "The downstream LKB1 signaling factors SIK2 and BRSK1/2 did not appear to be mediated by the tumor scaffold compared to TCP." (PMID 35755802, 2022). "Importantly, reducing SIK2/3 by itself did not significantly affect normal eye tissue growth of animals fed HDS, indicating that SIK2/3 is functionally required for Ras/Src-tumor growth in the presence of HDS." (PMID 26573956, 2015).
cancer (35 papers, 2015 to 2025). A tumor composed of atypical neoplastic, often pleomorphic cells that invade other tissues. "Salt‐inducible kinase 2 (SIK2; also known as serine/threonine‐protein kinase SIK2) is overexpressed in several cancers and has been implicated in cancer progression." (PMID 35278271, 2022). "Another proposed mechanism underlying the metabolic relation between cancer cells and adipocytes is the activation, via autophosphorylation, of the salt-inducible kinase 2 (SIK2), a member of the AMP-activated protein kinase (AMPK) family." (PMID 34440886, 2021). "The association of high SIK2 levels with RFS was more significant for basal cancer patients (n=353; p=6.7×10-5) compared to the Luminal A and Luminal B subtypes." (PMID 29774109, 2018). "SIK2 is overexpressed in several cancers and has been implicated in cancer progression." (PMID 35278271, 2022). "Additionally, as HR deficiency might make cancer cells more susceptible to treatments that damage DNA, SIK2 inhibitors can work in concert with conventional chemotherapeutic drugs." (PMID 40612876, 2025). "Given its involvement in metabolic pathways and potential roles in cancer progression, SIK2 expression may indirectly influence tissue characteristics, aiding in risk stratification, treatment selection and prognosis assessment, thus positioning SIK2 as a promising prognostic marker and drug target." (PMID 39578642, 2025). "Inhibiting the expression of SIK2 with SIC-19 significantly reduced the percentage of GFP+ cancer cells, and homologous recombination repair ability was weakened." (PMID 40612876, 2025). "Colonization of omental tissue depends on expression of salt-inducible kinase 2 (SIK2) in cancer cells." (PMID 37448521, 2023). "Cell experiments indicate that sustained release of HG from Gel Nap‐S+HG induce a prominent therapeutic effect on cancer cells by inhibiting SIK2 and phosphorylation of their downstream signaling molecules." (PMID 35618488, 2022). "Measurement of PARP enzyme activity indicated that the SIK2 inhibitors enhanced the effect of olaparib by further decreasing PARP enzyme activity in cancer cells with detectable PARP protein levels." (PMID 35642638, 2022). "The adipocyte-rich microenvironment favors OC metastasis through fatty acid oxidation and salt-inducible kinase 2 (SIK2)-mediated PI3K-AKT cancer cell proliferation/survival." (PMID 36557213, 2022). "Together, these results suggest that SIK2 inhibitors enhance the vulnerability of cancer cells to olaparib, not only by inhibiting PARP enzyme activity but also by blocking the class-IIa HDAC/MEF2D–mediated DNA repair function." (PMID 35642638, 2022). "Mechanistically, SIK2 regulated cancer cell motility and migration by myosin light chain kinase, smooth muscle (MYLK)‐meditated phosphorylation of myosin light chain 2 (MYL2)." (PMID 35278271, 2022). "To explore the underlying mechanism of m6A demethylase FTO-mediated autophagy in ccRCC, we identified SIK2 as a key regulator that plays a decisive role in malignant tumor proliferation and distant metastasis including lung metastasis." (PMID 36263177, 2022). "Cancer cells co‐cultured with adipocytes also showed increased SIK2 phosphorylation at S358, and increased expression of SIK2, MYL2‐pS19 and MYLK‐pS343." (PMID 35278271, 2022). "Together, these results suggest that preventing DNA DSB repair by SIK2 inhibitors enhances the vulnerability of cancer cells to PARP inhibition." (PMID 35642638, 2022). "Together, these findings demonstrate that FANCA‐deficient cells are dependent upon SIK2 for survival, supporting a preclinical rationale for targeting of SIK2 in FA‐disrupted cancers." (PMID 34058059, 2022). "Knockout of SIK2 sensitized cancer cells to olaparib judged by lower IC50 for olaparib in SIK2-deficient cells compared with control cells." (PMID 35642638, 2022).
cancer (continued). "Here, we found that MRIA9, a newly developed small-molecule inhibitor of the salt-inducible-kinase 2, interferes with the cell division of cancer cells." (PMID 34359562, 2021). "At the cancer-adipose tissue interface, adipocytes of the omental tissue induce the calcium-mediated activation of SIK2 in ovarian cancer cells." (PMID 34440886, 2021). "SIK2 is overexpressed in several cancer cell lines and boosts cancer cell tolerance to different stresses, such as deprivation of nutrients and taxol chemotherapy." (PMID 30723708, 2019). "In this mini-review, we discuss the results of in vivo and in vitro studies regarding the SIK2 mechanism in different signaling pathways, particularly their regulation of cancer cells." (PMID 30723708, 2019). "Clinical and pathological data indicate that SIK2 is a potential oncogenic marker in ovarian, prostate, osteosarcoma, and colorectal cancers by controlling different cellular mechanisms." (PMID 30723708, 2019). "Taken together, these studies point towards a possible dichotomous role of SIK2 in cancer progression and metastasis." (PMID 29774109, 2018). "Since SIK2 was previously suggested as an important modulator of autophagosome maturation, its role in cancer cell survival through regulating autophagy requires further investigations." (PMID 29774109, 2018). "We tested a panel of clinically approved tyrosine kinase inhibitors used for treating various human cancers for their ability to also inhibit SIK2 and SIK3 in vitro." (PMID 25351958, 2015). "Building on SIK2’s role in glucose metabolism in cancer, we hypothesized its similar influence in fibroblasts." (PMID 40868174, 2025). "This study demonstrated the functions of SIK2 in vivo by constructing SIK2+/– mice, laying a foundation for further study of SIK2 protein function, and providing a potential target for the treatment of cancer radiotherapy, immune dysfunction and other diseases." (PMID 37706195, 2023). "To confirm whether SIK2 inhibitors induce DNA damage in cancer cells by inhibiting DNA repair, we tested the effect of SIK2 inhibitors on olaparib-mediated induction of DNA DSBs." (PMID 35642638, 2022). "Therefore, the mechanisms by which SIK2 regulates cancer cell motility in other cancer sites need to be further explored." (PMID 35278271, 2022). "Furthermore, SIK2 has been identified as a mitotic regulator by influencing the centrosome function, and several studies described an oncogenic role of SIK2 in many cancer types." (PMID 34359562, 2021). "Furthermore, SIK2 promotes cancer cell proliferation and metastatic progression via the activation of the PI3K/AKT pathway." (PMID 34440886, 2021). "Increasing evidence suggests that SIK2 modulates a wide variety of biological functions and acts as a signal transmitter in several pathways important to tumorigenesis and progression of cancer cells and can execute pro‐ or anti‐tumorigenic effects dependent on cell type or context." (PMID 33128264, 2021). "Considering that fatty acid and cholesterol function as the major building blocks and signaling molecules which are required in cancer cells, we propose that the SIK2-regulated fatty acid and cholesterol synthesis may be involved in the OC growth." (PMID 31932581, 2020). "Recent studies have unraveled the role of SIK2 in cancer development and progression." (PMID 31932581, 2020). "Our findings indicate the potential application of SIK2 as a therapeutic target for cancers." (PMID 30723708, 2019). "Since SIK3 is homologous to SIK1 and SIK2, further studies were conducted to determine whether a broader requirement exists for SIKs in cancer." (PMID 30723708, 2019). "We have identified salt-inducible kinase 2 (SIK2) inhibitors, ARN3236 and ARN3261, which decreased DNA double-strand break (DSB) repair functions and produced synthetic lethality with multiple PARP inhibitors in both homologous recombination DNA repair deficiency and proficiency cancer cells." (PMID 35642638, 2022).
cancer (continued). "SIK2 targeting may be applied as a novel strategy for treating multiple cancer types." (PMID 30723708, 2019). "Thus, the dichotomous function and mechanism between SIK2 and cancer must be further elucidated." (PMID 30723708, 2019). "However, the mechanisms underlying the reduction of SIK2 levels in cancer tissues were not discussed." (PMID 30723708, 2019). "By contrast, stable ectopic expression of SIK2 in SKOv3 and OVCAR8 cell lines desensitized cancer cells to olaparib, evidenced by an increased IC50." (PMID 35642638, 2022). "The SIK2 inhibitor, ARN‐3236, was used to further assess the effect of SIK2 on cancer cell migration and motility." (PMID 35278271, 2022). "SIK2 is required for centrosome splitting and PI3K activation and regulates cancer cell proliferation, metastasis, and sensitivity to chemotherapy." (PMID 35642638, 2022). "Consistently, our results demonstrated that SIK2 promoted fatty acid synthesis of OC cells through up-regulation of FASN, which further support FASN as a critical oncogene in cancer progression." (PMID 31932581, 2020). "The SIK2 inhibitors HG-9-91-01, ARN-3236, and KIN-112 have succeeded in cancer therapy approaches, validated in cultured cells and in vivo animal models, although additional optimization of these small molecules is required for therapeutic investigation." (PMID 30723708, 2019). "SIK2 upregulation is activated by the phosphoinositide 3-kinase (PI3K)-Akt signaling pathway, which regulates glucose metabolism, and the overexpression of this pathway leads to cancer cell proliferation." (PMID 36731029, 2023). "SIK2 protein expression was positively correlated with the expression of MYL2‐pS19 (r = 0.87; Pearson correlation coefficient, P = 0.01) and MYLK‐pS343 (r = 0.83, Pearson correlation coefficient, P = 0.02) in these cancer cell lines." (PMID 35278271, 2022). "Taken together, SIK2 inhibition decreases PARP enzyme activity and the expression of FANCD2, EXO1, and XRCC4, suggesting that the combination of a SIK2 inhibitor and PARP inhibitor has the potential to increase the magnitude and duration of PARP inhibitor activity in patients with different cancers." (PMID 35642638, 2022). "Given the observation that loss of SIK2 caused GC cells to act more aggressively, we suspected that these changes might result from the ability of SIK2 to suppress EMT, an important step for cancer cell metastasis." (PMID 33128264, 2021). "Activated SIK2 phosphorylated acetyl-CoA carboxylase (ACC) and phosphatidyl inositol 3 kinase (PI3K) and, thus, simultaneously regulates both fatty acid oxidation and cancer cell proliferation and survival." (PMID 30765860, 2019). "However, the exact role of SIK2 in cancer cell motility, migration and metastasis is not fully understood." (PMID 35278271, 2022). "Although in this study SIK2 is found to contribute to cellular autophagy and EMT in GC, detailed molecular mechanisms by which they functionally interact with each other cooperatively to regulate downstream signaling for cancer progression remain to be fully elucidated." (PMID 33128264, 2021). "Mechanistically, SIK2 could phosphorylate Drp1 at the Ser616 site and suppress the mitochondrial OXPHOS pathway, thus suggesting that mitochondrial fission mediated by the phosphorylation of Drp1 plays an important role in impairing the OXPHOS pathway and promoting cancer development." (PMID 36192752, 2022). "Earlier investigations demonstrate that SIK2 maintains cell homeostasis via modulation of cAMP response element binding protein (CREB)-mediated gene transcription during starvation, which may be a possible mechanism for cancer cell survival under stress, such as chemoradiotherapy." (PMID 30723708, 2019). "Our hit list contains genes coding kinases with established oncogenic functions such as MET, EGFR, AKT, mTOR, RSK2 as well as genes that do not (yet) have an established role in cancer progression (NEK5, SIK2)." (PMID 27374095, 2016).
SIK2 also shares sentences with these, for which no sentence is quoted: Cerebral ischemia (2 papers); type 2 diabetes (2); Arthritis (1); autoimmune disease (1); benign tumors (1); cerebral infarction (1); cholelithiasis (1); cholestasis (1); diffuse large B-cell lymphoma (1); gastric adenocarcinoma (1); gynecological disease (1); heart failure (1); Hepatic steatosis (1); hepatoma (1); Hyperinsulinemia (1); hypertriglyceridemia (1); hypertrophy (1); Hypoglycemia (1); infection (1); inflammatory bowel disease (1); invasive mammary carcinomas (1); kidney disease (1); leukemia (1); lipodystrophy (1); metabolic disease (1); metastatic tumors (1); myocardial infarction (1); renal cell carcinoma (1); Sepsis (1).